ENSG00000252677
Synonyms: LOC124900411
Gene: Small nucleolar RNA gene on chromosome 18 (21,711,950 to 21,712,119, reverse strand). Ensembl gene ENSG00000252677.
Gene Ontology:
Biological process: RNA processing
Cellular component: nucleolus
Homologues: Orthologues: rat LOC120096125 (65% identical), mouse Gm26040 (49% identical), rat LOC120096127 (43% identical). Paralogues in human: SNORA81 (69% identical).